LEP (leptin)
Diseases named in the same sentence as LEP in open-access papers (continued):
Sharing a sentence is not in itself a finding about the gene and the disease.
Obesity (continued). "Dysregulation in cellular programming can lead to an excess of adipocyte formation, contributing to obesity, such as leptin can regulate Plin5 M6A methylation by promoting FTO to affect the lipid metabolism and energy consumption." (PMID 39390356, 2024). "Disruption of the hypothalamic circuits controlling body weight and appetite caused by mutations in the genes encoding leptin, LEPR, POMC and MC4R can lead to severe obesity in humans." (PMID 39526054, 2024). "Given the significant roles of adipokines, particularly leptin and adiponectin, in the pathogenesis of obesity and related disorders, it is crucial to assess their connections with the two studied lncRNAs." (PMID 38167433, 2024). "Leptin’s role beyond appetite regulation involves signaling potential resistance patterns in obesity." (PMID 38178093, 2024). "Our findings indicate that several cytokines, including IL-5, IL-17A, IL-22, IL-33, TNF-α, leptin, and IL-10 were independently influenced by asthma and obesity." (PMID 39902293, 2024). "Elevated leptin levels and the accumulation of unsaturated fatty acids typical of obesity lead to alterations in CD4+ T cells, resulting in their dysfunction and eventual apoptosis." (PMID 39000296, 2024). "In girls (278 with normal weight, 126 with overweight, and 61 with obesity), from normal weight to obesity, plasma leptin and LAR increased significantly (p < 0.001), while plasma adiponectin decreased without significant differences (p = 0.483)." (PMID 38289144, 2024). "Given that LepRb‐expressing neurons are sparse in the PVH, it is unlikely that SH2B1 in the PVH protects against obesity by directly enhancing leptin signaling." (PMID 38885417, 2024). "The impaired leptin signaling in obesity disrupts normal ovarian function and further contributes to infertility in PCOS patients." (PMID 39767708, 2024). "RAC1 was characterised by the presence of obesity, and upregulation of the complement pathway and leptin signalling." (PMID 39401856, 2024). "In summary, the studies point to increased inflammation, Aβ and APP elevated levels, and leptin resistance as the sharing characteristics between obesity and AD." (PMID 38933275, 2024). "Leptin, a 16 kDa adipocyte-derived adipokine, is considered a potential marker for obesity-related complications such as atherosclerosis and neuropathy." (PMID 38672227, 2024). "Obesity may contribute to proximal GC development through several mechanisms, including obesity-associated gastro-esophageal reflux, insulin resistance, dysregulation of the levels of leptin, adiponectin, and ghrelin, and elevated levels of insulin-like growth factor (IGF)." (PMID 38339127, 2024). "The intricate balance between pro-inflammatory adipokines like leptin and resistin, and anti-inflammatory adipokines like adiponectin and omentin, underscores a pivotal aspect of obesity’s impact on health." (PMID 39064298, 2024). "In obesity, adipocyte hyperplasia and increased leptin levels affect the leptin signaling receptor in the brain, developing so-called leptin resistance." (PMID 39000383, 2024). "The findings of this study suggest that supplementation with 30 g MPC per day for 8 weeks in women with obesity following a weight-loss diet resulted in reductions in BMI, WC, fat mass, FBS, insulin, LDL-C, and leptin, and an increase in HDL-C and adiponectin." (PMID 38831442, 2024). "Obesity-induced high leptin levels can negatively impact androstenedione synthesis in the ovarian cells and disrupt oocyte development and interaction with the surrounding cells." (PMID 38892561, 2024). "Most of the studies supporting the benefits of exercise in obesity are due to the downregulation of leptin and/or an improvement in leptin resistance." (PMID 39058075, 2024). "A previous study also showed that children with obesity had significantly lower Ob-R levels and higher leptin levels." (PMID 39062791, 2024).
Obesity (continued). "Obesity manifests as a condition characterized by chronic inflammation and elevated levels of insulin, lipids, and leptin." (PMID 38892653, 2024). "The positive correlation we observed between leptin levels and energy, carbohydrate, and sugar intakes suggests a potential mechanism for leptin resistance in obesity." (PMID 39700087, 2024). "It has been reported that mothers with a normal body weight had lower leptin, adiponectin, and partly different miRNA levels than mothers with overweight/obesity." (PMID 39458514, 2024). "Further, leptin, a hormone produced by adipose tissue, is often elevated in obesity but with reduced sensitivity at the hypothalamus due to leptin resistance." (PMID 39840189, 2024). "In models of mice with high-fat-diet-induced obesity, a decrease in leptin concentrations and expression levels has been reported following treatment with 6-gingerol or with freeze-dried fresh ginger." (PMID 39334752, 2024). "Leptin resistance is related to human obesity owing to downregulated receptors or post-receptor implications." (PMID 38353886, 2024). "This resistance stems from obesity-related processes that impair leptin function, hindering its ability to reach target cells." (PMID 38397015, 2024). "On the other hand, despite these issues, key insights into leptin physiology and resistance and their role in obesity would have been seen as important discoveries." (PMID 38165042, 2024). "Recently, controversial opinions on the clinical benefit of increasing leptin sensitivity in the context of obesity have been given." (PMID 38643150, 2024). "Early studies mainly explored obesity-causing genes from a single-gene perspective, and >20 causative genes have been confirmed to be highly associated with the development of obesity, including FTO, PPARG2, LEP, MC4R, and POMC." (PMID 39389470, 2024). "Currently, three primary mechanisms have been postulated to establish a link between obesity and cancer, encompassing insulin resistance, adipokines—most notably, leptin and adiponectin—and chronic inflammation." (PMID 38977823, 2024). "It exhibits antagonistic action to leptin and its levels decrease in obesity due to positive energy balance." (PMID 38951515, 2024). "Since leptin is mainly produced by adipose tissue, a common metabolic change observed in obesity is the increase in leptin concentration in blood." (PMID 39000383, 2024). "Here we report that the SEL1L-HRD1 protein complex of the highly conserved ER-associated protein degradation (ERAD) machinery in POMC neurons is indispensable for leptin signaling in diet-induced obesity." (PMID 38260335, 2024). "This condition of leptin resistance is commonly observed in obesity and contributes to its progression." (PMID 39700087, 2024). "Second, statistical analysis showed that leptin levels in serum were significantly increased in individuals with obesity (SMD 1.03; 95% CI 0.72–1.34 ng/mL)." (PMID 39684379, 2024). "Leptin is another well-known adipocyte derived adipokine that acts as a neural regulator of obesity, metabolic function and feelings of satiety." (PMID 39175574, 2024). "Because obesity regulates the levels of adipokines such as adiponectin and leptin, qRT-PCR was used to analyze the levels of these adipokines in both the lungs and gonadal white adipose tissue." (PMID 39065704, 2024). "Lean humans have SLR that binds to the majority of circulating leptin, while individuals with obesity often have lower SLR concentrations, leading to increased plasma leptin levels and reduced responsiveness to leptin's effects." (PMID 39183855, 2024). "Since obesity is usually associated with elevated leptin levels, the most likely thymus impairments may be caused by the development of leptin resistance or inhibitory effects of glucocorticoids, which may be additionally produced in adipose tissue during obesity." (PMID 39061983, 2024).
Obesity (continued). "The finding of a positive correlation between insulin resistance and leptin concentration prompted the use of its concentration as a marker in the diagnosis of obesity and diseases related to it." (PMID 38396961, 2024). "The regulation of energy balance is managed by the central nervous system, which integrates satiety cues along with obesity‐related signals like leptin and insulin." (PMID 39606796, 2024). "Elevated levels of AT-secreted leptin in women with obesity suppress insulin-induced ovarian steroid production and inhibit the pro-estradiol production of the luteinizing hormone (LH)." (PMID 39456156, 2024). "Inflammatory adipokines such as leptin and resistin are elevated in obesity, contributing to insulin resistance." (PMID 39770936, 2024). "All studies show a greater association between leptin and excessive GWG in individuals living with overweight and obesity compared to those with normal weight." (PMID 38999894, 2024). "A study was conducted to investigate the effects of ASs on obesity in male Wistar rats, focusing on body weight, glucose levels, insulin, and leptin." (PMID 39449954, 2024). "They identified sequences of leptin secretory events through deconvolution of measured plasma leptin levels in women with obesity and compared the reconstructed leptin levels over time with the measured data." (PMID 39281006, 2024). "Obesity in BBS patients involves the dysregulation of the hypothalamic leptin–melanocortin signaling pathway." (PMID 38397265, 2024). "In obesity, AT can lead to aberrant expression of adiponectin, leptin, and other adipokines through epigenetic modifications." (PMID 38405061, 2024). "While endothelial leptin signaling is considered protective against neointima formation in a healthy state, obesity-induced leptin resistance can shift this balance toward an atherogenic phenotype." (PMID 38397015, 2024). "Our findings have important implications for understanding the effects of lifestyle modification on leptin regulation and obesity." (PMID 39444577, 2024). "Exercise is known to improve leptin sensitivity, which can be diminished in individuals with obesity due to leptin resistance." (PMID 39599699, 2024). "This study aims to show the relationship between the LEP gene and the leptin hormone and explain the epigenetic mechanisms of its protective effect against obesity." (PMID 39594868, 2024). "It was reported that obesity increases the blood volume through the adipose tissue producing various bioactive substances and hormones, such as leptin, which can lead to an increase in blood volume." (PMID 38541014, 2024). "Leptin resistance is typified by diminished satiety, increased nutrient intake, and subsequent weight gain, ultimately contributing to the development of obesity." (PMID 38899007, 2024). "On the other hand, the effects of leptin on glucose homeostasis in the context of obesity and insulin resistance are mediated by POMC-expressing neurons within the hypothalamic arcuate nucleus." (PMID 38707092, 2024). "In obesity, similarly to insulin resistance, disruptions in leptin signaling occur, resulting in leptin resistance and high levels of leptin in plasma." (PMID 39544693, 2024). "For participants with overweight/obesity pBMI, only leptin median concentrations differed significantly between GWG categories (Kruskal–Wallis test, p = 0.038)." (PMID 38999894, 2024). "A large number of studies have reported the relationships between leptin levels and diabetes or obesity." (PMID 39684379, 2024). "For this search, we used broad terms like: “genetic obesity”, “obesity”, “leptin-melanocortin pathway”, “pharmacotherapy”, “glucagon-like peptide-1”, “naltrexone-bupropion”, “naltrexone”, “bupropion”, “anti-obesity agents”, and “anti-obesity medication”." (PMID 39050109, 2024). "Overall, given PTP1B's critical role in insulin and leptin signaling, it is considered an excellent target for treating obesity and diabetes." (PMID 39238503, 2024).
Obesity (continued). "Obesity-related high leptin expression and insulin resistance are also correlated with the prognosis of type 2 diabetes." (PMID 39518420, 2024). "While level of adiponectin which exerts protective effects against obesity-related breast cancer progression is reduced, expression of leptin is strongly increased in obese state." (PMID 39253073, 2024). "Plasma leptin levels were significantly increased (p = < 0.0001) and significantly correlated with the BMI in the obesity cohort." (PMID 38172514, 2024). "In turn, aldosterone enhances MR-induced expression of leptin and other cytokines, modulating inflammatory status and visceral fat dysfunction and contributing to the development of obesity-related hypertension." (PMID 38186879, 2024). "The relationship between obesity and TC was also investigated studying leptin and its receptor in papillary thyroid cancer (PTC)." (PMID 38392069, 2024). "Male neonate rats supplemented with physiological doses of leptin during lactation were more resistant to the development of overweight/obesity." (PMID 38786092, 2024). "CEMs are of value to prevent the progression to mild-to-moderate obesity, hypertriglyceridemia, and leptin resistance in overweight individuals." (PMID 38398818, 2024). "Obesity-related cancer development occurs due to an imbalance in adipokines, characterized by increased production of leptin (oncogenic adipokine) and reduced release of adiponectin (anti-oncogenic adipokine)." (PMID 39410536, 2024). "Accordingly, serum leptin, as a marker of obesity development, increases (at a trend level) only with the introduction of a larger dose of cholesterol into the diet." (PMID 38791421, 2024). "These associations align with the existing literature that emphasizes leptin’s role in energy homeostasis and its involvement in the pathophysiology of obesity-related complications." (PMID 39771030, 2024). "More recently, leptin has emerged as a potential activator of NOX5-derived ROS production in human epithelial mammary cells, linking obesity-associated hyperleptinemia with mammary tumorigenesis." (PMID 38542437, 2024). "This mini-review focuses on the potential impact of PM2.5 exposure on the TLR4 signaling pathway, its contribution to leptin resistance, and dysbiosis that exacerbates the link between obesity and AD." (PMID 38933275, 2024). "Certain micronutrients, macronutrients, and bioactive dietary compounds have the capacity to enhance leptin sensitivity and counteract leptin resistance in individuals with obesity." (PMID 39768256, 2024). "The development of obesity in mice fed WD was also reflected by the significantly increased plasma levels of the hormones leptin, peptide YY (PYY), resistin, and glucose-dependent insulinotropic polypeptide (GIP)." (PMID 38469142, 2024). "Another study showed that 11-HETE exhibited a positive correlation with body mass index, waist circumference, and elevated serum leptin levels in individuals with obesity." (PMID 39188949, 2024). "STAT3 is a transcriptional factor critical to a major signaling pathway generating the anti-obesity effects of leptin." (PMID 39590343, 2024). "Leptin levels are increased with obesity and are secreted in direct proportion to the adipose tissue mass." (PMID 39272654, 2024). "Leptin, often referred to as the obesity gene, is situated at 7q31.3 and plays a crucial role in regulating obesity by suppressing food intake and enhancing energy expenditure." (PMID 38615017, 2024). "At week 16, there were increases in inflammatory (TNF-α in adipose tissue) and obesity (serum leptin, serum L/A ratio) markers." (PMID 39598339, 2024). "Leptin is an adipocyte-derived hormone, and obesity leads to elevated leptin levels, which stimulates increased sympathetic nerve activity, leading to increased heart rate and blood pressure." (PMID 38784171, 2024).
Obesity (continued). "Imbalances, such as elevated ghrelin or leptin resistance, can contribute to overeating and obesity, highlighting their crucial roles in appetite regulation and metabolic health." (PMID 39125390, 2024). "One dimension of AT dysfunction, secretory adiposopathy, often assessed as a low plasma adiponectin (A)/leptin (L) ratio, is commonly observed in obesity." (PMID 38481206, 2024). "Finding increased levels of leptin and IL-6 in ADS in association with BMI-defined obesity supports a direct BMI effect on peritumor AT." (PMID 39408921, 2024). "Changes in leptin and ADPN levels have been found to be associated with allergic airway responses and to serve as key substances linking obesity and asthma." (PMID 38365763, 2024). "Leptin levels are also increased in pregnant women with obesity compared with lean pregnant women, contributing to leptin resistance during pregnancy." (PMID 39083072, 2024). "Targeting leptin in obesity, T2DM, and cardiometabolic disorders offers significant therapeutic potential by addressing leptin resistance and restoring its physiological functions." (PMID 39682585, 2024). "Leptin is an obesity-related hormone secreted from the adipose tissue that manages energy balance, neuroendocrine and immune system operations, and glucose, lipid, and bone metabolism." (PMID 38791252, 2024). "Leptin was found to positively correlate with IL-6 and TNFα levels, as well as with clinical parameters of obesity (i.e., body mass index (BMI) and abdominal circumference)." (PMID 38247541, 2024). "Leptin, secreted by adipocytes, activates the JAK/STAT pathway by binding to the long-form leptin receptor and SOCS3 represents a potential mechanism for leptin-resistant obesity." (PMID 38975347, 2024). "Our results suggest that an inadequate quantity of leptin is responsible for obesity of the patient." (PMID 39041042, 2024). "Obesity was found to promote tumor progression by increasing leptin expression synergized with decreasing adiponectin expression." (PMID 38405061, 2024). "Raised leptin levels synchronicity with obesity is typically interpreted as a sign of leptin resistance because leptin reduces body weight and food intake." (PMID 40259963, 2024). "And the condition of being obesity leads to a state of meta‐inflammatory characterized by heightened levels of proinflammatory cytokines, glucose, leptin, fatty acids metabolism." (PMID 38923758, 2024). "In the present experiment, we confirmed that during obesity progression, ovarian leptin signalling regulates NLRP3 inflammasome activation and the expression of genes regulating M1 macrophage infiltration." (PMID 38580672, 2024). "Nonetheless, leptin has been proposed as a potential link between obesity and the development of cardiovascular disease by modulating a number of components of the cardiovascular system such as the heart and vasculature." (PMID 38256208, 2024). "These substances, including leptin and adiponectin, are collectively referred to as adipokines, which regulate obesity and cardiovascular diseases." (PMID 38392211, 2024). "Lacticaseibacillus rhamnosus PL60 supplementation increased signals of apoptosis, and uncoupling protein levels in adipose tissue, and serum leptin, which can contribute to reducing obesity." (PMID 38732619, 2024). "Subsequent investigations into the impact of SF-1 on leptin signaling and the development of obesity, especially under high-fat diet conditions, further informed on the multifaceted role of SF-1 in metabolic adaptation." (PMID 39479520, 2024). "Previous studies have shown that Cel reduces the obesity of HFD-fed diabetic obese (db/db) and leptin-deficient (ob/ob) mice by inhibiting endoplasmic reticulum stress and increasing STAT3-dependent leptin signaling." (PMID 38881873, 2024). "Neuroendocrine substances such as ghrelin and leptin are involved in regulating appetite and energy balance, which are significant in the context of obesity and MDD." (PMID 38892598, 2024).